BCL6 (BCL6 transcription repressor)
Diseases named in the same sentence as BCL6 in open-access papers (continued):
Sharing a sentence is not in itself a finding about the gene and the disease.
endometriosis (continued). "Based on the results of this exploratory study, the feasibility of using BCL6 and SIRT1 as protein markers in bodily fluids (such as serum, cervical swab, and urine) for a non-invasive diagnosis of endometriosis is relatively low." (PMID 34698105, 2021). "However, if the endometrial overexpression of BCL6 and SIRT1 in patients with endometriosis could be extended to levels of BCL6 and SIRT1 in their serum or plasma, the diagnosis of the disease could be made significantly less invasive and more accessible to patients." (PMID 34698105, 2021). "In turn, reduced expression of GLI1 was shown in the endometrium of women with endometriosis, confirming a mechanistic role for STAT3, BCL6, and SIRT1 overexpression in the P4 resistance of endometriosis." (PMID 31387263, 2019). "Together with SIRT1 and BCL6, KRAS was overexpressed in the eutopic endometrium of women with endometriosis." (PMID 29750165, 2018). "In the present study, we report that BCL6 and SIRT1 are over-expressed and co-localize in the nuclei of endometrial cells from women with endometriosis." (PMID 28754906, 2017). "Our group reported that BCL6 is highly overexpressed in the endometrium of women with endometriosis during the secretory phase of the menstrual cycle compared to women without endometriosis." (PMID 39903727, 2025). "Given the similarities between endometriosis and adenomyosis and the increased expression of KRAS in both conditions, it is hypothesized that the BCL-6 protein may also be increased in adenomyosis." (PMID 39903727, 2025). "The key oncogenes B-cell lymphoma 6 (BCL6) and BCL9 may play a role in endometriosis as well as in the placenta, another tissue type characterized by invasion and proliferation." (PMID 39684461, 2024). "The BCL6 test has similarly shown promising outcomes as well; however, it is specific to endometriosis, and therefore is not generalizable to all patients experiencing infertility." (PMID 37240919, 2023). "Increased endometrial BCL6 has been recently considered to be a negative predictor for patients with endometriosis undergoing IVF." (PMID 36294483, 2022). "On the contrary, use of BCL6 as a protein biomarker in bodily fluids (such as serum and urine) for a less invasive diagnosis of endometriosis is not appropriate." (PMID 36294483, 2022). "All the previous studies describing BCL6 expression in the endometrium of women with or without proven endometriosis use HSCORE for the quantification of BCL6 staining." (PMID 36294483, 2022). "In fertile or infertile women without endometriosis, BCL6 intensities were spread in a narrow range, with a median at 34.980 (range 11.033–78.448) and at 14.786 (range 0.724–48.51), respectively." (PMID 36294483, 2022). "BCL6 was chosen based on its previously reported elevated expression in endometrial biopsies, and SIRT1 is co-expressed and upregulated in the endometrium of women with endometriosis." (PMID 34698105, 2021). "Furthermore, BCL6 and SIRT1 are over-expressed in the eutopic endometria of women with endometriosis." (PMID 34698105, 2021). "The average BCL6 concentration in serum for patients without endometriosis was 1953.8 pg/mL with a sample size of ten." (PMID 34698105, 2021). "In searching for a less invasive diagnostic tool for endometriosis, our investigation built upon previous work that demonstrated increased levels of BCL6 in eutopic endometria of patients with endometriosis compared to endometria without endometriosis." (PMID 34698105, 2021). "Analysis of these expression differences resulted in the development of an H-SCORE immunohistochemistry cutoff of >1.4 to define the difference in BCL6 expression between women with endometriosis and those without." (PMID 34698105, 2021).
endometriosis (continued). "To determine that SIRT1 and BCL6 proteins are overexpressed as part of endometriosis development, we performed immunohistochemical analysis of SIRT1 and BCL6 in eutopic baboon endometrium sequentially after the experimental induction of the disease (n = 4 per time point)." (PMID 28754906, 2017). "In addition, sirtuin 1 (SIRT1), a histone deacetylase and gene silencer, co-localizes with BCL6 in the nuclei and is upregulated in the endometrium of women and non-human primates with endometriosis." (PMID 37108154, 2023). "Once transcribed, BCL6, with the help of SIRT1, could inactivate regulators of progesterone but also lead to implantation defects and repeated miscarriages in patients with endometriosis." (PMID 36294483, 2022). "Moreover, the highest HSCORE for BCL6 expression was found in infertile women suffering from endometriosis as compared to infertile women without endometriosis." (PMID 36294483, 2022). "In order to test the efficiency of our new digital method of quantification, we compared endometrial BCL6 expression between fertile and infertile women without or with different stages of endometriosis by using the widely used HSCORE analysis and our new automatic digital image analysis." (PMID 36294483, 2022). "Although the majority of patients with endometriosis have been found to present an aberrant BCL6 expression, the same may also occur in the absence of evident endometriosis." (PMID 35054432, 2021). "While the vast majority of patients with endometriosis exhibited aberrant BCL6 expression, it cannot be ruled out that abnormal expression may occur in the absence of evident endometriosis." (PMID 32266059, 2020). "To determine whether SIRT1 physically interacts with BCL6, we performed immunoprecipitation with SIRT1 antibody in total protein lysates from Ishikawa human endometrial adenocarcinoma cell line and endometrium from endometriosis patients." (PMID 28754906, 2017). "Interestingly, high levels of endometrial BCL6 in women with unexplained infertility have been recently revealed as demonstrated and confirmed in our study by the higher expression of this factor in our infertile group of patients without endometriosis." (PMID 36294483, 2022). "Furthermore, sirtuin 1 (SIRT1), a transcriptional regulator associated with both oncogenic and tumor-suppressor roles, binds and co-localizes with BCL6 and is also up-regulated in endometrium from women and non-human primates with endometriosis, significantly correlating with BCL6 expression levels." (PMID 31387263, 2019).
lupus (26 papers, 2014 to 2025). "By the way, DNA binding sites for MEF2A and BCL6 were significantly enriched in systemic lupus erythematosus susceptibility loci." (PMID 38255677, 2023). "E4BP4 deficiency in CD4+ T cells in lupus resulted in overexpression of BCL-6, which promoted Tfh cell differentiation and function and exacerbated pristane-induced lupus-like diseases." (PMID 35637283, 2022). "In autoimmune status, Bcl-6 deficiency in lupus-prone mice has been found to impair lupus-like symptoms, and increased Bcl-6 has been observed in lupus circulating Tfh-like cells, which is positively correlated with disease activity." (PMID 30410493, 2018). "Importantly, manipulation of Bcl6 expression and thus Tfh cell generation or adoptive transfer of lupus-associated Tfh cells from Roquinsan/san mice into healthy recipients induces the formation of GCs, highlighting a contributing role of Tfh cells in SLE." (PMID 30158933, 2018). "In fact, in support of our observation, a recent study used a KO for Bcl6 to block the formation of GC B cells in an induced lupus model." (PMID 39163122, 2024). "Accordingly, we also observed that the cells with the highest AIM2 levels were AIM2+ TFH‐like cells (CD4+PD1+Bcl6+AIM2+) in lupus patients." (PMID 35343082, 2022). "Overall, we provided supporting evidence that BCL-6 is a novel factor participating in the pathogenesis of lupus by epigenetically suppressing miR-142-3p/5p expression with the help of EZH2 in CD4+ T cells." (PMID 35637283, 2022). "Our previous studies revealed that TET2 enrichment on the BCL6 promoter was attributed to IL‐21, which potentially explains why lupus T cells have higher BCL6 expression." (PMID 35343082, 2022). "A new mechanism revealed by us indicates that BCL-6 recruits EZH2 to the promoter of miR-142 in CD4 + T cells in lupus to increase the expression of miR-142-3p/5p." (PMID 35637283, 2022). "IL‐21 can enhance the recruitment of the hydroxymethyltransferase TET2 in the promoter region of BCL6 in lupus patients." (PMID 35343082, 2022). "We demonstrated that the overexpression of BCL-6 in CD4+ T cells in lupus decreased the expression of miR-142-3p/5p, and inhibition of miR-142-3P/5P, and led to increased expression of IL-21." (PMID 35637283, 2022). "BCL-6 attaches to the promoter region of miR-142 in CD4+ T cells in lupus and recruits EZH2 and HDAC5, which leads to the upregulation of H3K27me3 and the downregulation of H3K9/K14ac, respectively." (PMID 35637283, 2022). "mTORC1 is found to be highly activated and AICDA, its transcriptional activator PAX5, and BCL6 are overexpressed in a population of atypical memory B cells in patients with active lupus." (PMID 33557396, 2021). "Possible fates of differentiation of naive T cells in lupus include development into TFH cells under the transcriptional regulation of Bcl6 to interact with B cells to produce autoantibodies, or maturation into effector Th17 subsets." (PMID 29593732, 2018). "It is reported that the mRNA level of Bcl-6 is moderately expressed in systemic lupus erythematosus and rheumatoid arthritis, but the mRNA level of Blimp-1 is very low." (PMID 26503442, 2015). "Some lupus drugs may inhibit autoantibody production by modulating BCL-6 expression in CD4+ T cells." (PMID 35637283, 2022). "Apart from Bcl6 and Aicda (Aid), Gm614 is highly expressed in GC B cells from lupus-prone mice." (PMID 33193409, 2020). "Lupus mice also showed a decreased frequency of CXCXR5+PD1+Bcl6+Foxp3+ TFR relative to TFH cells." (PMID 30348969, 2018). "Similar to what was observed in the SRBC-immunized BALB/c mice, blocking ICOS signaling led to a significant decrease in number of both GC B cells (∼65% reduction, p<0.01) and Tfh (CD4+ CD44high CXCR5+Bcl6+) cells (∼70% reduction, p<0.01) in this spontaneous autoimmune model of lupus." (PMID 25101629, 2014).
lupus (continued). "Together, our findings reveal that AIM2 is highly expressed in the B cells of lupus patients and promotes B-cell differentiation by modulating the Bcl-6–Blimp-1 axis, providing a novel target for SLE treatment." (PMID 34521812, 2021). "Transcription factor B cell lymphoma 6 (BCL6) is a master regulator of T follicular helper (Tfh) cells, which play a crucial role in the pathogenesis of systemic lupus erythematosus (SLE)." (PMID 33568199, 2021). "In addition, in our previous study, we found that IL-21 can increase TET2 enrichment on the promoter region of Bcl-6, which might explain the increased levels of Bcl-6 in lupus T cells." (PMID 30410493, 2018). "Follicular helper T cells (Tfh), a critical subset of CD4+ T cells in lupus, are characterized by high expression of CXCR5, PD-1, interleukin-21 (IL-21), and the specific transcription factor BCL6." (PMID 40989817, 2025). "IFNγR−/− Roquinsan/san mice showed prevented lupus development, evidenced by low number of Tfh cells and reduced ANA production, whereas IFNγR+/+ Roquinsan/san mice upregulated the Bcl-6 expression in Tfh cells." (PMID 38164134, 2023). "The expression of Absent in melanoma 2 (human AIM2 and murine Aim2) is found to be increased in TFH‐like cells (CD4+Bcl6+PD1+) in the peripheral blood and skin lesions of lupus patients, compared to healthy controls." (PMID 35538881, 2022). "Nevertheless, the study of regulatory networks involving BCL-6 and EZH2 in lupus remains a major challenge at the genome level." (PMID 35637283, 2022). "In fact, IL‐21 increases the recruitment of TET2 to the BCL6 promoter region in lupus patients, while interferon (IFN)‐α, the signature cytokine for lupus, also increases AIM2 levels, albeit to a lesser degree." (PMID 35538881, 2022). "In skin lesions, higher mRNA levels of AIM2 and TFH‐related genes, including BCL6, IL21 and STAT3, were found in lupus patients than in NCs." (PMID 35343082, 2022). "The 2DG plus metformin combination also reduced Bcl6 and PD-1 expression in total CD4+ T cells from these lupus strains." (PMID 30348969, 2018). "Tight regulation of Bcl6 expression, an essential transcription factor for T follicular helper (TFH) cells, is critical as aberrant TFH cell expansion is associated with autoimmune diseases, such as systemic lupus erythematosus (SLE)." (PMID 28811467, 2017). "As the TC lupus-prone model, W.Yaa mice presented an expanded population of CD4+CD44+FOXP3–CXCR5+BCL6+CD162lo/–PD-1+ Tfh cells as well as follicular Tregs (CD4+CD44+FOXP3+CXCR5–BCL6–CD162lo/–PD-1+ Tfr), with a skewed Tfh/Tfr ratio, none of which were altered by DON." (PMID 40956613, 2025). "Given the effect of the cooperation of BCL-6 and EZH2 on miR-142-3p/5p expression in CD4+ T cells in lupus, we wondered whether EZH2 could be a therapeutic target for lupus treatment." (PMID 35637283, 2022). "As BCL-6, IL-21, CD40L and ICOS are all critical regulators involved in the differentiation and maturation of Tfh cells, these findings are helpful for understanding the role that Tfh cells play in lupus." (PMID 35637283, 2022). "Moreover, the importance of the interaction between BCL-6 and IL-21 in Tfh cell differentiation and autoantibody production should not be ignored, especially in lupus and some autoimmune diseases." (PMID 35637283, 2022).
ovarian carcinoma (23 papers, 2018 to 2025). A malignant neoplasm originating from the surface ovarian epithelium. "The transcription factor B-cell lymphoma 6 (BCL6) is critically associated with poor prognosis and cisplatin resistance in ovarian cancer treatment." (PMID 38169532, 2024). "For example, our list included BCL6, which displays pro-oncogenic activity in ovarian cancer, and CHD4, which is associated with apoptosis mediated by cisplatin in ovarian cancer cells." (PMID 38844966, 2024). "The expression level of BCL6 in ovarian cancer is correlated with the FIGO staging which is associated with the invasiveness of tumor." (PMID 30420967, 2018). "Reports showed that BCL6 may be a novel diagnostic and treatment strategy for breast or ovarian cancer." (PMID 32206063, 2020). "For example, USP14 promotes resistance to cisplatin of ovarian cancer by increasing the stability of BCL6 protein." (PMID 39928282, 2025). "In ovarian cancer, high BCL6 expression correlated with high tumor burden and poorer prognosis, with similar associations identified in the context of high-grade glioma." (PMID 39456751, 2024). "Remarkably, WK369 significantly induced the upregulation of BCL6 target genes in vivo, which is consistent with our in vitro data observed in ovarian cancer cells treated with WK369, confirming the BCL6 inhibitory effect of WK369 in vivo." (PMID 38169532, 2024). "We not only validated the efficacy of the identified BCL6 inhibitor WK369 as a monotherapy for ovarian cancer, but also provided a potential therapeutic option for the use of targeted agents in adjuvant chemotherapy." (PMID 38169532, 2024). "Here, we developed a novel BCL6 small molecule inhibitor, WK369, which exhibits excellent anti-ovarian cancer bioactivity, induces cell cycle arrest and causes apoptosis." (PMID 38169532, 2024). "It inhibits ovarian cancer cell apoptosis by stabilizing the level of BCL6, which increases ovarian cancer cisplatin resistance." (PMID 37143582, 2023). "The overexpression of BCL-6 induces proliferation, migration, and invasion in ovarian cancer cell lines." (PMID 34961030, 2021). "In view of our finding that NAC1 and BCL6 are co-upregulated in ovarian cancer specimens and cell lines, we wanted to test the possibility that NAC1 modulates the expression of BCL6." (PMID 32412910, 2020). "This study identified a new mechanism by which NAC1 binds to BCL6 and attenuates BCL6 auto-downregulation, thus upregulating the expression levels of BCL6 in ovarian cancer cells." (PMID 32412910, 2020). "We propose that the co-upregulation of NAC1 and BCL6 works in concert as a transcription complex to modulate an array of their downstream genes that play critical roles in the malignant phenotype of ovarian cancer." (PMID 32412910, 2020). "BCL6 induces cell proliferation, migration and invasion when overexpressed in ovarian cancer cell lines." (PMID 32412910, 2020). "To answer this question, we first performed an endogenous NAC1 and BCL6 ChIP on the consensus BCL6 binding sequence within the BCL6 promoter in ovarian cancer cells." (PMID 32412910, 2020). "Prompted by our finding that NAC1 and BCL6 are co-transcriptional regulators, we investigated their expression patterns in a panel of ovarian cancer cell lines and HGSC specimens, using qPCR and immunohistochemistry respectively." (PMID 32412910, 2020). "Our analysis also identified a novel function of NAC1 in attenuating BCL6 auto-downregulation in ovarian cancer." (PMID 32412910, 2020). "It was shown that BCL6 was overexpressed in ovarian cancer, promoting proliferation, migration and invasion of tumor cells." (PMID 32412910, 2020). "This work reveals that dysregulation of LINC00152 in ovarian cancer predicts poor survivals of patients, and the stabilization of BCL6 by LINC00152 promotes ovarian tumor proliferation and invasion." (PMID 33282727, 2020).